FTO (FTO alpha-ketoglutarate dependent dioxygenase)
Diseases named in the same sentence as FTO in open-access papers (continued):
Sharing a sentence is not in itself a finding about the gene and the disease.
Obesity (continued). "Interaction accounted for 2.88% and 21.62% of the occurrence of obesity and central obesity when a long-time LTSB existed with FTO rs9939609." (PMID 33668547, 2021). "Notably, FTO is a risk factor for PCOS that is independent of its correlation with BMI or obesity." (PMID 34150765, 2021). "Hence, it may be plausible to expect that the association between FTO polymorphism and colorectal cancer may be independent of its association with obesity-related traits." (PMID 34650918, 2021). "Therapeutic targeting of the thermogenesis and orexigenic or anorexigenic pathways that are regulated by the FTO and TUB genes respectively has important clinical implications for the obesity epidemic especially in ethnic minorities." (PMID 33983957, 2021). "Therefore, it is not clear, whether the FTO gene methylation in region 1 contributes to increasing the risk of developing obesity and, indirectly, also diseases associated with excessive body weight." (PMID 34063412, 2021). "Moreover, in our previously published results, we observed that dietary carbohydrate, protein, and fat intake may modulate the impact of FTO genetic SNPs on obesity and obesity-related metabolic consequences; therefore, we decided to perform additional analyses, including on dietary fiber intake." (PMID 34829664, 2021). "After mapping the human genome, broad association studies (GWAS) have managed to identify a variety of genes involved in the etiology of obesity, among them MC4R, FTO, and PPAR family genes." (PMID 34422027, 2021). "This research examined the changes in FTO gene expression upon Ramadan intermittent fasting (RIF) in a group of metabolically healthy subjects with overweight and obesity." (PMID 35372458, 2021). "Thus, the advent of FTO may well explain the relationship between obesity and breast cancer." (PMID 33292526, 2020). "FTO alpha-ketoglutarate dependent dioxygenase (FTO), one of the crucial elements in modulating body weight and fat mass, is correlated with obesity and body mass index (BMI)." (PMID 32522250, 2020). "The expression level of each of the five obesity-related genes (SH2B1, GNPDA2, FTO, TMEM18, and KCTD15) in three cancer tissues (HNSC, LIHC, and CHOL) was higher than that in the corresponding normal tissues." (PMID 33299884, 2020). "The expression levels of other eight obesity-related genes (TMEM18, KCTD15, GNPDA2, SH2B1, FTO, LEP, PCSK1, and GPR120) in about half types of cancer tissues were higher/lower than those in the corresponding normal tissues." (PMID 33299884, 2020). "Selectively inhibiting FTO by inhibitors decreases FOXO1 expression and reduces body weight and fat mass in a high-fat diet-induced obesity (DIO) mouse model." (PMID 31936903, 2020). "The FTO protein is an Alk‐B like DNA/RNA demethylase, FTO knock‐out mice survive until adulthood stages and exhibit no differential weight changes when compared to wild‐type mice, suggesting that alterations in protein structure do not indicate a risk of obesity." (PMID 31033179, 2019). "In this study, we investigated the genetic link between the SNPs rs9939609 of FTO and rs1544410 of VDR genes with the obesity phenotype in the Emirati population for the first time." (PMID 29343214, 2018). "Therefore, rs9939609 variant was not the major decisive factor of PCOS, and FTO might influence PCOS through an association with obesity." (PMID 28451524, 2017). "In this study, we investigated the relationship between variation of the FTO and IRX genes and obesity in Poles." (PMID 28662178, 2017). "Here we have assessed gene-environment interaction effects of FTO and MC4R on obesity, taking into account any modulation due to age and gender." (PMID 28384342, 2017). "However, the direct causality between FTO and obesity has not been clearly validated." (PMID 28988979, 2017). "Therefore, we investigated whether the FTO risk variant may not be associated only with obesity and BMI, but also with elevated nocturnal blood pressure." (PMID 26324055, 2016).
Obesity (continued). "Recently it has been reported that a long-range interaction between intron 1 of FTO and enhancer of the homeobox gene IRX3 governs IRX3 gene expression, thus influencing cell fate decisions leading to obesity." (PMID 27390851, 2016). "Regarding the FTO variants-T2D association, while several studies have reported that the association between the variants and risk of T2D remained significant after adjustment for BMI, a surrogate measure of obesity, others could not confirm this finding." (PMID 27820839, 2016). "However, a recent study suggested that the obesity-associated FTO variants affect expression of IRX3, but not FTO, in the human brain, which may mean that FTO is not the causal gene in this region." (PMID 26363598, 2015). "Homozygote risk-allele carriers (AA) of the FTO single nucleotide polymorphism (SNP) rs9939609 showed a 1.67-fold increased risk to develop obesity in comparison to non-risk-allele carriers (TT) which could be reproduced for several FTO SNPs in different ethnic populations." (PMID 26431034, 2015). "Rs16953002, located in 31kb from exon 9 and over 146kb from exon 8 of FTO, was once reported to be associated with melanoma in European population (per-allele OR for A = 1.16), but till now, no other research has yet reported its role in obesity or breast cancer risk." (PMID 26146447, 2015). "Recently, the combined effect of FTO rs9939609 and MC4R rs17782313 has been discussed in relation to obesity, breast cancer and endometrial cancer." (PMID 26032905, 2015). "In this study, we focused on the role of FTO on energy balance in the VMH, a hypothalamic nucleus involved in obesity, fear, and female reproductive behavior." (PMID 25501432, 2014). "Thus, in both settings loss of FTO protects against obesity independent of the presence of leptin." (PMID 25144618, 2014). "Further studies on FTO in PCOS patients will provide possible interpretation for its etiology and interaction of obesity and PCOS." (PMID 23840863, 2013). "The FTO and MAF genes have been recently described to be major candidate genes for human obesity, and these results have been replicated in multiple populations." (PMID 23840443, 2013). "Sanger sequencing of PCR products of all FTO and SH2B1 exons and their flanking regions were performed in 338 Chinese Han children with obesity and 221 age- and sex-matched lean controls." (PMID 23825611, 2013). "However, it is not known whether genetic variants in genes encoding fat and obesity-associated (FTO), leptin (LEP), and leptin receptor (LEPR) associate with physical performance, and whether fitness level modifies the risk for obesity associated with these gene variants." (PMID 23284729, 2012). "When the population was stratified by SCM type (excluding subjects with the rare TY type; 0.6% of our study population), we observed different relationships of FTO and MC4R with obesity-related phenotypes." (PMID 19822564, 2011). "However, aswith the case of FTO and BMI, common variants modulatinganthropometric traits often explain only a small amount of the observed phenotypicvariation.It is likely that variation at PLIN4 is yet another contributor tothe complex nature of obesity and its associated comorbidities." (PMID 21533135, 2011). "In this study, we evaluated the potential regulation of FTO and NAMPT as two novel candidates potentially involved in the pathophysiology of obesity and metabolic sequelae by metabolic regulators at the level of adipocytes." (PMID 21687707, 2011). "However, whether FTO plays a role in obesity needs further investigation." (PMID 21103374, 2010). "We genotyped nine SNPs reported in GWAS of obesity and/or T2D, including SNPs in HHEX, KCNJ11, SLC30A8, FTO, CDKN2, CDKAL1, TCF2, and the rs9300039 SNP in an intergenic region, in 561 colon cancer cases and 721 population controls." (PMID 27990199, 2009).
Obesity (continued). "In humans, fat mass, and genetic markers for obesity genes MC4R and FTO, are strongly related to bone mineral content, total body and regional, measured by DXA." (PMID 19878575, 2009). "Besides the more thoroughly studied function of FTO/IRX3 is the involvement in adipocyte precursor development and obesity and diabetes pathogenesis." (PMID 40943660, 2025). "Notably, FTO-knockout mice exhibit enhanced thermogenic capacity and resistance to high-fat diet (HFD)-induced obesity." (PMID 40646807, 2025). "In contrast, our results showed decreased FTO expression levels in PBMCs from children with obesity, with a significant negative correlation observed with BMI and waist and hip circumference." (PMID 40806129, 2025). "Anthropometric characteristics, metabolic characteristics, and FTO rs9939609 genotype frequencies, according to obesity (non-obese vs. obese/overweight)." (PMID 39925495, 2025). "The degree of senescence exhibited by FTO was significantly greater in obese samples compared to the control group of individuals without obesity." (PMID 39820532, 2025). "Similar findings have been reported in adipose tissue, where a significant negative correlation was observed between FTO expression in adipose tissue and total carbohydrate intake in subjects with and without obesity." (PMID 40806129, 2025). "This study aimed to investigate the gastric expression of FTO and MC4R genes and their association with circulating levels of leptin, adiponectin, and ghrelin in individuals with and without obesity." (PMID 41423640, 2025). "Mutations/variations in the FTO, but not the ALKBH5, gene are linked to diabetes and obesity, and it is possible that the different product selectivities of the two oxygenases reflect their different biological roles in disease." (PMID 40874592, 2025). "Regarding FTO, boys with obesity had lower expression than boys without obesity (p < 0.001) and girls without obesity (p < 0.001) but higher expression than girls with obesity (p = 0.039)." (PMID 40806129, 2025). "Conversely, studies in adolescent and adult patients with overweight and obesity have reported no significant changes in FTO expression in PBMCs and adipose tissue compared to normal weight subjects." (PMID 40806129, 2025). "A cohort study showed that the FTO rs9939609 SNP has no significant impact on obesity-related metabolic traits." (PMID 40662170, 2025). "This study investigated the association between gastric expression of FTO and MC4R genes and circulating levels of leptin, adiponectin, and ghrelin in individuals with and without obesity." (PMID 41423640, 2025). "This FTO-m6A-H19/IGF2 circuit may explain paradoxical GWAS findings linking FTOrs9939609-A to both leanness and obesity." (PMID 40055326, 2025). "Boys without obesity showed higher FTO expression than girls with or without obesity (both p < 0.001), and girls with obesity had reduced levels compared to girls without obesity (p < 0.001)." (PMID 40806129, 2025). "Furthermore, numerous studies have identified the epigenetic modifications on various robust genes like the FTO, NBPF3, and SREBF1 were related to obesity, suggesting the regulatory role of genetic factors in obesity-associated methylation changes." (PMID 40702573, 2025). "While upregulation of FTO has been reported in some contexts related to diabetes, such as obesity, it is not universally observed across all diabetic complications." (PMID 40356725, 2025). "Given that FTO plays a crucial role in metabolism and obesity, it is not surprising that FTO dysregulation also significantly impacts tumorigenesis." (PMID 39744011, 2024). "Lastly, as the study focused on adolescents with overweight and obesity, the results do not provide insights into the role of the FTO gene in preventing obesity among adolescents." (PMID 38556726, 2024). "We genotyped FTO rs9939609 SNP in cheek swabs collected from 49 women aged 18–35, equally with and without overweight and obesity." (PMID 39671348, 2024).
Obesity (continued). "For instance, in comparison to FTO, ZFHX3 has approximately 1 million base-pairs closer to Iroquois homeobox protein 3 (IRX3), which is known to mechanistically interact with the genetic variation of FTO to influence obesity and related metabolic disorders." (PMID 39060932, 2024). "Although the mechanism explaining the potential connection between FTO and adiponectin is not clearly defined, individuals with obesity or elevated BMI often show reduced levels of adiponectin." (PMID 39253342, 2024). "Regarding CLOCK/CT, FTO/AT, GHRL/GT, LEP/GA, LEPR/AG, MC4R/CT we found intermediates values for weight, BMI, waist circumference, and WHR, reflecting moderate levels of body fat and obesity." (PMID 39203789, 2024). "As more gene sequencing data emerges, the relationship between FTO genes and obesity seems to hold true for certain populations but not others, and its manifestation also appears to be dependent on other diet and lifestyle factors, such as exercise." (PMID 37702886, 2023). "This prompts the hypothesis that the FTO gene may contribute to PCOS development, possibly via its impact on BMI or obesity." (PMID 37710301, 2023). "FTO/YTHDC2 activates the transcription of thermogenesis genes and facilitates the browning of white fat by promoting the expression of HIF1A, which is conducive to fighting obesity by increasing energy expenditure." (PMID 36830642, 2023). "A study from 2017 reported that hypomethylation of the FTO non-promoter region is an early marker of T2D and another study showed that hypomethylation induces overeating, fat accumulation, and obesity." (PMID 37614712, 2023). "The only exception is rs7204609, rs3764261 and rs7799039 SNPs of FTO, CRPT and LEP genes, the negative effect sizes (β = -0.155, -0.125, -0.103Kg/m2) indicate BMI lowering, obesity protective effect of their minor allele." (PMID 36126070, 2022). "In a diet-induced obesity mouse model, feeding entacapone with FOXO1 mRNA as a direct-acting substrate for FTO induced intrahepatic glycogen xenobiogenesis and adipose tissue thermogenesis, resulting in reduced body mass and fasting glucose concentrations in mice." (PMID 36118041, 2022). "Accordingly, no causal associations were identified between obesity and cortical or posterior subcapsular (PSC) cataracts, whereas FTO was putatively involved in nuclear cataract pathogenesis." (PMID 36572895, 2022). "Therefore, the aim of our study was to analyze the genome expression and methylation of FTO and PLAG1 genes in children with obesity." (PMID 34063412, 2021). "As a result, it is fair to speculate that the FTO gene may have a role in the pathogenesis of PCOS via BMI and/or obesity." (PMID 34563259, 2021). "FTO expression did not correlate with high-energy intake, waist circumference, or obesity as shown by the binary logistic regression analysis performed." (PMID 35372458, 2021). "We are not aware of other studies on genotype effects of FTO on hepatic IS measured with tracer-technology in healthy individuals with obesity." (PMID 33684170, 2021). "On the contrary, among Mizo, the risk caused by the interaction of FTO rs9939609 and MC4R rs17782313 for obesity was enhanced, albeit with no statistical significance." (PMID 34414818, 2021). "The main molecular mechanism of FTO gene on body weight, BMI, and obesity has not yet been elucidated." (PMID 34399781, 2021). "The status of FTO in obesity alone does not reveal an effect, especially when the level of IRX3 is changed through FTO knockdown or overexpression." (PMID 33162550, 2020). "In this context, findings from the current study are consonant with evidence suggesting that FTO obesity SNPs per se do not influence parameters of insulin resistance." (PMID 33348678, 2020). "Besides the FTO, Melanocortin 4 Receptor (MC4R) and Transcription Factor 7-Like 2 (TCF7L2) genes are the two commonly studied candidate genes for obesity and T2D." (PMID 32397403, 2020).
Obesity (continued). "In parallel, we also would like to make the point that any anti-obesity therapy via blocking FTO function can have negative effects on the proper function of the hippocampus." (PMID 30730976, 2019). "In human brain samples tested, these obesity-related variants showed an association with expression levels of IRX3, but surprisingly not with FTO as previously predicted." (PMID 29741584, 2018). "Conversely, FTO obesity SNPs have not been related to energy expenditure, with evidence suggesting that those carrying the risk allele do not show reduced basal metabolic rate or physical activity levels." (PMID 29686893, 2018). "The unfavorable FTO AA genotype was not significantly more common in the group of patients with overweight and/or obesity." (PMID 29675043, 2018). "Like FTO, MC4R has been extensively studied in obesity research." (PMID 28615046, 2017). "The significance of FTO rs17817449, GNB3 rs5443 and MC4R gene mutation in Saudi obese populations has not been examined despite its association with obesity in other parts of the world." (PMID 29937877, 2017). "So it is reasonable to assume that FTO gene might play a role in the pathogenesis of PCOS via BMI and/or obesity." (PMID 28826396, 2017). "Studies have shown the importance of both FTO rs9939609 and 2D : 4D as a surrogate marker for obesity and coronary heart disease but none have studied the relationship between them." (PMID 28607773, 2017). "None of the other interactions between the FTO SNPs and fat and protein energy percentages, glycemic index and dietary fibre on obesity traits and T2D were statistically significant (Pinteraction > 0.05 for all interactions)." (PMID 27274759, 2016). "Thus, further studies are necessary to answer the question if either FTO or IRX3, or both are “the” obesity gene(s)." (PMID 26431034, 2015). "Using 4C-seq, investigators showed that enhancers located within an intron of the FTO gene and harboring obesity and T2D GWAS-identified SNPs do not interact with the FTO promoter but instead interact with the IRX3 gene which is located 500 Kb downstream." (PMID 26719772, 2015). "Obesity-linked SNPs were associated with IRX3 expression in these samples, but not with expression of FTO, directly linking these variants to IRX3 regulation." (PMID 25265168, 2014). "The associations of 23 SNPs located within 17 candidate genes (MTHFR, PPARγ, LPL, INSIG, TCF7L2, FTO, KCNJ11, JAZF1, CDKN2A/B, ADIPOQ, WFS1, CDKAL1, IGF2BP2, KCNQ1, MTNR1B, IRS1, ACE) with overweight and obesity, diabetes, metabolic phenotypes, and MetS were examined in both studies." (PMID 24959828, 2014). "This indicates that body weight development towards obesity is delayed by about three months when FTO is absent." (PMID 25144618, 2014). "Although no attention has been paid to the influence of the FTO locus on protein synthesis or lean mass in human obesity studies, our observation that milk fat and protein yield are affected is in agreement with the phenotype of FTO knock-out mice." (PMID 23691044, 2013). "However, the results may suggest that the regulation of FTO expression in the hypothalamus and heart reflect different mechanisms with the former demonstrating sensitivity to manipulation by dietary factors such as a high fat diet or perhaps by the resultant obesity and increased adiposity." (PMID 24019958, 2013). "This part of our study further showed that administration of a high fat diet and the resultant obesity failed to alter myocardial FTO expression." (PMID 24019958, 2013). "The role of FTO in general mechanism and epigenetic regulation suggests that FTO may be a pleiotropic factor involved in various diseases such as PCOS, obesity and T2DM." (PMID 23840863, 2013). "The rare missense mutations of FTO and SH2B1 did not confer risks of obesity in Chinese Han children in our cohort." (PMID 23825611, 2013).